TERT (telomerase reverse transcriptase)
Diseases named in the same sentence as TERT in open-access papers (continued):
Sharing a sentence is not in itself a finding about the gene and the disease.
tumor (continued). "Histopathological and molecular characterization of tumors was achieved considering tumor grade according to 2016 WHO and several biomarkers (i.e., IDH-1, TERT, MGMT, DEL1p/19q, Ki-67)." (PMID 35720068, 2022). "Although BRAFVal600Glu as a tumor driver event alone may not significantly affect patient outcome, its co-existence with the TERT promoter mutation results in the formation of aggressive PTC and even promotes the evolution of PTC to poor-differentiated tumors or ATCs." (PMID 33669363, 2021). "The treated tumor showed several CNVs in driver genes, including amplifications in MCL1, TERT, CCND1, AKT1, MYC, EGFR, and FGFR3; deletions in CDK1B, CDKN2A and CDKN2B; a PIK3CA hotspot mutation; and a high TMB." (PMID 34680239, 2021). "A treated tumor and a skin metastasis sample were obtained in the 16th month, and both showed MCL1, TERT, and MDM4 amplifications." (PMID 34680239, 2021). "HBV integration led to an evident upregulation of TERT, CCNE1, and FGB in the tumor (compared to the adjacent tissue)." (PMID 34642322, 2021). "Moreover, in the BC cell lines, we detected a positive correlation between TERT and PD-L2 across all tumor stages, suggesting a TERT-PD-ligand regulatory loop that might confer to tumor cells expressing high levels of PD-L1/L2 a longer lifespan through telomerase reactivation." (PMID 35223454, 2021). "Our observation of the most-often recurring integration sites such as TERT and MLL4 in tumors as well as FN1 in non-tumor tissues is compatible with previous reports." (PMID 34209079, 2021). "Our analysis identified several genes with recurrent HBV integration, including TERT, MLL4, ADAM12, PREX2, and SCFD2 in tumor tissues." (PMID 34209079, 2021). "The expression of TERT and TERC in normal cells is small, but the expression of TERT and TERC in tumor cells is indeed very substantial." (PMID 33869033, 2021). "Collectively, we have identified metabolic biomarkers of TERT and ALT status that provide a way of integrating critical oncogenic information into non-invasive imaging modalities that can improve tumor diagnosis and treatment response monitoring." (PMID 33397920, 2021). "As critically short telomeres are a hallmark of genomic instability associated to carcinogenesis and may be considered a marker of field cancerization, is not surprising that patients harbouring the -124 C>T TERT promoter mutation showed a significantly increased risk of tumour relapse." (PMID 34858860, 2021). "Primary NB tumor harbored, in addition to high-grade amplification of six loci besides MYCN, the atypical 5p15 gain containing TERT gene." (PMID 34830942, 2021). "In this review, we examine the evidence for genomic, phenotypic, and tumor microenvironment ITH in HCC, with a focus on two of the top molecular drivers of HCC: β-catenin (CTNNB1) and Telomerase reverse transcriptase (TERT)." (PMID 34771685, 2021). "TERT and MYC mRNA abundance was positively correlated (ρ = 0.27; P = 1.46 × 10−3) but MYC abundance was unrelated to tumour TL." (PMID 34824250, 2021). "It was found that TERT‐induced miR500A mediated the down‐regulation of PTCH1, GLI3 and CUL3, while miR500A directly targets the 3′UTR of PTCH1, promoting tumour invasiveness." (PMID 33713376, 2021). "We next analyzed associations between VMP1 expression and clinical pathological parameters, including the tumor grade, isocitrate dehydrogenase (IDH) status, 1p/19q codeletion, TERT status, and O6-methylguanine DNA methyltransferase (MGMT) promoter status." (PMID 34311746, 2021). "In order to evaluate telomerase activity specifically in CSCs, we compared the expression levels of TERT and TERF1 in CSCs versus bulk tumor cells in three human PDX-derived primary PDAC cell lines (Panc215, Panc185, Panc354)." (PMID 34201898, 2021). "Thirdly, important molecular characteristic data including TERT, 1p/19q LOH and ATRX were unobtainable because of tumor tissue status." (PMID 33596518, 2021).
tumor (continued). "Nanopore sequencing of tumor detected ten breakpoints, of which HBV was integrated into intergenic nearest CCNE1 in nine reads and into TERT promoter-TSS in one read." (PMID 34642322, 2021). "Gene amplification (e.g., EGFR, TERT, MYC, and ERBB2) was identified in tumor samples from 10 patients but was present only in paired tumors for one patient." (PMID 34109114, 2021). "Most vaccines that use these TERT-derived peptides were found to have major histocompatibility complex (MHC) I and MHC II epitopes specific to the tumor." (PMID 32674474, 2020). "Altogether, these results indicated that the expression of PUF60 and TERT showed a positive correlation in both RCC cell lines and tumor tissues." (PMID 33061812, 2020). "In this review, we discuss CD4 T cell responses against telomerase reverse transcriptase (TERT), a ubiquitous tumor antigen." (PMID 32630460, 2020). "A proposal would be to target the induction of TERT-specific memory T cells with stem-like characteristics (TSCM) and tumor-resident memory T cells (TRM), two subsets with strong antitumor properties that were reported to be involved in the response to ICPi." (PMID 32630460, 2020). "We identified six TAA protHLAIp that were exclusively detected in the tumor tissue of C3N-02289 (BIRC5, TERT, FAP, SPAG4, MAGEA9, and BCL2L1)." (PMID 32157095, 2020). "Most adult SHH cases belonged to the SHH-δ subtype which was highly enriched for TERT promoter mutations and had relatively favourable survival, further substantiating the hypothesis that adult SHH tumours represent a biologically disparate entity from paediatric and infant SHH tumours." (PMID 33172502, 2020). "An accompanying study of the pan-cancer analyses of whole genomes demonstrated intra-tumor heterogeneity is generally widespread and tumor subclones contain drivers, such as the TPM activated TERT gene, that are under positive selection." (PMID 32575418, 2020). "With the present study, we aimed at expanding our ongoing investigation on the role of TERT and TA in FOSCC by treating tumor cell lines with the specific inhibitor BIBR1532 and evaluating its potential anti-cancer activities." (PMID 33553285, 2020). "To identify a suitable tumour-specific promoter for the generation of an advantageous replication conditional HSV-1, we explored the CXCR4, Survivin/BIRC5 and TERT genes, known for their high level of expression in tumours." (PMID 32152425, 2020). "In addition, TERT inhibition in cell culture led to telomere shortening, as well as cellular apoptosis and inhibition of cancer cell growth, thus providing additional evidence that telomerase is fundamental for cancer cell immortalization and tumor progression." (PMID 32806719, 2020). "In the upstream TERT promoter, hypermethylation of a CpG (cg11625995, −628 of the AUG) has been used as a reliable biomarker for TERT expression, tumor progression, and prognosis." (PMID 33245585, 2020). "Some regulators, including tumor activators and suppressors, can regulate SP1 binding activity to TERT promoter to enhance or inhibit TERT transcription in HCCs23–26." (PMID 33239622, 2020). "Prime examples are the use of tumor-specific promoters such as carcinoembryonic antigen (CEA), telomerase reverse transcriptase (TERT) or Survivin promoters, which are active in cancer cells, but silent in differentiated healthy cells." (PMID 32674264, 2020). "Thus, therapeutic effectiveness of targeting TERT in antineoplastic treatment could be exploited besides its role on telomere length maintenance, circumventing the delayed therapeutic effects that are inherent to original tumor telomere length." (PMID 32722398, 2020).
tumor (continued). "We also found evidence for increased telomere length (tumor:normal ratio) in the majority of samples and disruption in either ATRX or DAXX or in the TERT promoter." (PMID 30889380, 2019). "It is worth noting that the number of tumours exhibiting BRAF K601E, TERT, RET/PTC1, and PAX8-PPARγ were too low to establish statistical significance." (PMID 31623671, 2019). "Frequently, TERT is used as a gene expression measure of TMM activity, e.g., to estimate tumor progression in CRC [see and references cited therein]." (PMID 31750255, 2019). "Both amplifications were reported to be genetic alterations that induce strong TERT and TERC overexpression in some tumours, although the specificity of these amplifications remains to be established." (PMID 29751586, 2018). "One study even reported canonical (− 228 and − 250) somatic TERT promoter mutations in the blood of multiple non-cancer patients, indicating that these events could even occur before the onset of cancer and act to prime the tumor bed." (PMID 29616301, 2018). "TERT promoter mutations preferentially occur in tissues with a lower rate of self-renewal and there are numerous reports on the extra-telomeric functions of TERT, including effects on the NF-κB and WNT/β-catenin pathway promoting tumor growth and invasiveness." (PMID 29616301, 2018). "Branched MAPs aimed at enhancing immune responses against tumor cells, including MAPs based on CTL epitopes of human telomerase reverse transcriptase (hTERT), are clearly observable." (PMID 29739434, 2018). "The predictive power is better than some existing prognostic factors in neuroblastoma, such as age, tumor stage, MYCN oncogene amplification and TERT expression." (PMID 30012197, 2018). "describe a novel hybrid tumor-specific promoter, ARE-hTERT, composed of thehuman TERT gene promoter (hTERT) and the antioxidant responseelement (ARE) from the human GCLM gene promoter." (PMID 29340219, 2017). "Many HBV integration events occurred near or within fragile sites and other repetitive regions, such as TERT, FN1, MLL4, ROCK1, CCNE1, SENP5, Alu sequences, and microsatellites, which are prone to tumor development and progression." (PMID 28382278, 2017). "When we analyze the gene expression data for these 8 extra samples, we see that TERT and MLL4 expressions are higher in tumor samples compared to the normal samples, relative to the samples where no such integration were found." (PMID 28361674, 2017). "These TERT/GFP+ cells showed enhanced stem cell-like properties both in vitro and in vivo, including tumor propagating capacity, metastatic activity and resistance to chemotherapeutic agents." (PMID 27102300, 2016). "A multivariate Cox regression model incorporating age, gender, cohort, KPS, tumor location, surgical history, TERT, and MGMT revealed that the interaction between TERT and MGMT was significant for OS in the combined GBM cohort of 453 cases." (PMID 27503138, 2016). "Both TERT- and VEGFR-2-specific cytotoxic T lymphocytes (CTL) were identified in an in vitro cytotoxicity assay, and the CTL activity against tumour cells was significantly elevated in the combined vaccine group." (PMID 26085010, 2015). "Compared with mannan-modified TERT adenovirus vaccine or mannan-modified VEGFR-2 adenovirus vaccine alone, the combined vaccine showed remarkably synergistic anti-tumour immunity in these models." (PMID 26085010, 2015). "Two human tumor cell lines highly expressing EphA3 and TERT(C4-2B and HGC27 cell) and cell line that expressed little EphA3 and TERT (2BS cell) were infected with Ad-TERTp-E1A-1504, Ad-TERTp-E1A-NC, or Ad-ΔE1A-1504 or Ad-ΔE1A-NC at the indicated titers." (PMID 25978371, 2015).
tumor (continued). "Reverse transcription-quantitative PCR (RT-qPCR) analyses demonstrated the presence of TERT mRNA at different abundances in all 6 examined MCC cell lines, and 15/15 frozen and 31/33 FFPE tumor specimens." (PMID 25301727, 2014). "TERT promoter sequencing was performed on 6 MCC cell lines and 43 tumor specimens from 35 patients with MCC." (PMID 25301727, 2014). "Further, this study also identifies the potential of the extracted polyphenols on major tumor progression molecular targets including NFκB, EGFR, kRAS, STAT3, VEGF, AKT, TERT, FGFA, BCl2 and PDGFA." (PMID 23613993, 2013). "In the tumours, the expression level of TINF2 was significantly lower than that of TERT (Two-sided Mann-Whitney U-test; U = 27, P = 0.03, median TINF2 = 0.51, median TERT = 3.58)." (PMID 22952882, 2012). "A second conclusion from these data are that the expressions of TERT, TRF2, TRF1, TIN2, and POT1 can be regulated by factors presumed to be at the tumor site, including mediators of stress (glucocorticoids) and inflammation (TNF-α)." (PMID 23342266, 2012). "We report the identification of 27 alternative transcripts of chicken TERT cloned during a comparison of three different chicken cell lines including MSB-1, a MDV tumor cell line." (PMID 20964812, 2010). "Tumor characteristics were assessed using immunohistochemical staining for CD79B, LC3, and TERT." (PMID 42113085, 2026). "The RAIR signature stratified TCGA tumours with graded activation of these programs and was largely independent of BRAF and TERT promoter status, while preserving pathway associations when transferred to DepMap." (PMID 42232186, 2026). "Although TERT MAF did not correlate with MRI tumor volume, contrast-enhancing tumors had increased TERT MAF-values, indicating more tumor DNA leakage from a more disrupted and thereby more permeable BBB." (PMID 40285800, 2025). "In addition, TERT also acts as a transcriptional modulator to regulate PI3K/AKT, Wnt/β-catenin and NF-kB signaling pathways, thereby promoting tumor progression." (PMID 40860184, 2025). "The presence of TERT promoter mutations in PDD false-positive samples were not statistically associated with age, gender, smoking history, tumor size, time to recurrence, pathological T classification, concurrent CIS, and grade." (PMID 40995307, 2025). "While six of the 11 patients who developed recurrences and finally DOD demonstrated TERT amplification, none of the patients who developed tumor recurrences and were categorized as AWD or NED exhibited TERT amplification." (PMID 40272676, 2025). "Metastatic tumor expansion into lymph nodes can occur independently of TERT amplification, a finding consistent with the lack of correlation of TERT amplification with tumor multifocality, which is known to increase the likelihood of developing LNMs in PTCs." (PMID 40272676, 2025). "The dynamics of TERT + immune cells, which are components of the TME, may reflect the tumor’s impact on overall immunity." (PMID 41417416, 2025). "In NB tumours with MNA, telomere maintenance is commonly achieved through re-expression of TERT, which is promoted by direct binding of MYCN to the E-box consensus sites within the TERT promoter region." (PMID 40713849, 2025). "Molecular markers now incorporated into the WHO CNS5 classification include TERT promoter mutations and CDKN2A/B deletions, which are sufficient to upgrade a tumor to WHO grade lll even in the absence of high-grade histologic features." (PMID 41552249, 2025). "None of the 19 cases without DMs that recurred exhibited TERT amplification and the existence of TPM revealed only a trend of association with tumor relapse (Log-rank P = 0.0914) (“Online resource – Figure-1”)." (PMID 40272676, 2025).
tumor (continued). "Among the non-canonical biological functions of TERT, it influences different components of the tumor microenvironment, including inflammatory factors and the immune response." (PMID 39858033, 2025). "To explore which transcription factors may be driving changes in transcriptional programming in TERT and ATRX altered tumours we performed binding motif enrichment analysis using single-nuclei ATAC-sequencing." (PMID 40097403, 2025). "Finaly, the tumor mutational burden (TMB) was low, and no abnormalities were detected in BRAF, NRAS, HRAS, NTRK1/2/3, RET, or TERT." (PMID 40277780, 2025). "Furthermore, the combination treatments (EGFR and TERT or EGFR and GABPB1) led to even greater tumor growth inhibition than the single treatments." (PMID 40463649, 2025). "Analysis of 159 patients with a 2-year follow-up revealed a negative correlation between PFS and tumor progression, consistent with TERT + leukocyte changes." (PMID 41417416, 2025). "The mean log2 of fold changes for mRNASeq read counts of 16 thyroid differentiation genes, as described in the TCGA study, was −0.287 for the TERT positive and −0.060 for the TERT negative tumor, respectively." (PMID 38642578, 2024). "All HN-PG/non-chromaffin tumours (defined by transcriptional profile) were excluded given the absence of TERT/ATRX alterations in these tumours." (PMID 38978571, 2024). "TERT exhibits non-canonical functions involved in tumor oncogenesis independent of telomerase activity, which is detailed in the following sections." (PMID 38278800, 2024). "Metastatic PPGLs with ATRX/TERT variants exhibited higher TMB and MSI, higher Ki-67 labeling index, and larger tumor size, compared to ATRX/TERT non-altered samples." (PMID 39466488, 2024). "Furthermore, we excluded low tumour purity cases (<50% estimated by WGS data) and a subclonal TERT-mutant case." (PMID 38978571, 2024). "The genomic profiles of both tumor lesions were consistent with HR-NB and showed several persistent segmental alterations, including 3p and 11q deletion, gain of CCND1, 7q, 17q, and an alteration at 5p indicating TERT juxtaposition." (PMID 39324010, 2024). "After vaccination with a single peptide from TERT, extensive epitope spreading into the entire TERT protein has been observed in the few patients achieving tumor regression, but not in non-responders." (PMID 38571942, 2024). "The tumor exhibited no IDH1, IDH2, TERT, H3, or BRAF mutation, and had no EGFR amplification, no MYB rearrangement, and a positive MGMT status." (PMID 39227460, 2024). "We confirmed that there was higher expression of TERT and TERC in the HT1080-LT xenograft tumours." (PMID 39728924, 2024). "Being able to inhibit TERT activation in tumor cells, the knockdown of ELF4 could represent a new therapeutic target in HCC with TERT promoter integration." (PMID 37108816, 2023). "Targeting TERT for cancer treatment is not a novel concept given the specificity of TERT expression in tumour cells for the maintenance of telomere length and the replicative potential." (PMID 37345011, 2023). "Telomerase reverse transcriptase (TERT) activation meets the criteria of oncogenic addiction in HCC and could be actionable therapeutic target and a relevant tumor antigen." (PMID 37516867, 2023). "Of the 10 tumor cases with aberrant TERT, only 1 scored negative with both antibodies (1/10; 10%), whereas the remaining 9 cases (9/10; 90%) exhibited some positivity for at least one antibody." (PMID 37486076, 2023).